HBP1 (HMG-box transcription factor 1)
Diseases named in the same sentence as HBP1 in open-access papers (continued):
Sharing a sentence is not in itself a finding about the gene and the disease.
depression (1 paper, 2025). "Through comprehensive molecular regulatory network analysis, transcription factors such as ATF1, IRF1, HBP1, DRAP1, TGIF2, and TFDP1 were identified as potential regulatory factors in depression, warranting further exploration." (PMID 40370590, 2025).
diabetes (1 paper, 2022). "However, when challenged with an HFD, the consumption of which is a key risk factor for T2DM, HBP1 knockout worsened the diabetes and fatty liver of the mice." (PMID 36326689, 2022). "Here, we found that HMG-box transcription factor 1 (HBP1) is involved in T2DM and that its deficiency in mice aggravates the features of diabetes." (PMID 36326689, 2022). "In addition, the data suggest that HBP1 may play a role in the development of other diseases in addition to tumors, such as diabetes." (PMID 36326689, 2022). "To characterize the relationship of the transcription factor HBP1 with T2DM, we measured HBP1 protein expression in the livers of db/db mice and HFD-fed mice, both of which develop diabetes." (PMID 36326689, 2022). "Next, we induced diabetes in C57BL/6J mice by feeding them an HFD for 3 months, thus creating a classical mouse model of T2DM, then collected livers from C57BL/6J mice fed the HFD or a normal diet for the measurement of HBP1 protein content by western blotting." (PMID 36326689, 2022).
epilepsy (1 paper, 2021). A brain disorder characterized by episodes of abnormally increased neuronal discharge resulting in transient episodes of sensory or motor neurological dysfunction, or psychic dysfunction. "Thus, we posed two questions: 1) are the metabolic and signaling mechanisms from the day 5 pilocarpine and kainate models also utilized in a potential HBP1 genetic model of epilepsy?" (PMID 34358226, 2021).
fibrosis (1 paper, 2021). the formation of excess fibrous connective tissue in an organ or tissue in a reparative or reactive process. "Collectively, these data suggested that miR‐155 promoted intestinal fibrosis by targeting suppression of HBP1." (PMID 33769664, 2021).
Hepatic fibrosis (1 paper, 2021). The presence of excessive fibrous connective tissue in the liver. "Our study found that HBP1-deficient mice developed more severe liver fibrosis." (PMID 33794968, 2021). "Masson staining and Sirius Red staining showed that hepatic fibrosis only occurred in the mouse group treated with DEN/CCl4, and more severe hepatic fibrosis occurred in HBP1-deficient mice." (PMID 33794968, 2021).
Hepatitis (1 paper, 2021). Inflammation of the liver. "This indicates that HBP1 has a certain protective effect on the normal function of the liver in the hepatitis caused by DEN/CCl4 treatment." (PMID 33794968, 2021).
Lymphatic Metastasis (1 paper, 2018). Transfer of a neoplasm from its primary site to lymph nodes or to distant parts of the body by way of the lymphatic system. "However, miR-29c and HBP1 gene expression in NPC patients was not significantly different between the different tumor TNM stages, and NPC patients with and without lymphatic metastasis (LNM) (both the middle and right side)." (PMID 29367693, 2018).
neurotoxicity (1 paper, 2022). Toxicity that causes injury to the central or peripheral nervous system or damages its function. "Hbp1‐related terms were involved in 2 periods of Neuronal alteration, Oxidative stress and Blood–brain barrier, and in 1 period of Metabolism and Neurotoxicity." (PMID 35899365, 2022).
osteoarthritis (1 paper, 2019). A noninflammatory degenerative joint disease occurring chiefly in older persons, characterized by degeneration of the articular cartilage, hypertrophy of bone at the margins and changes in the synovial membrane. "This study provides a framework for prioritization of GWAS variants and highlights a role of HBP1 and Wnt signaling in osteoarthritis pathogenesis." (PMID 31164647, 2019). "Fourth, we had previously prioritized HBP1 as a potential target in the 7q22 osteoarthritis-associated locus based on gene expression analysis." (PMID 31164647, 2019).
ovarian dysfunction (1 paper, 2022). The inability of the ovaries to function. "We herein discovered that HBP1 elevation counteracted the suppressive effects of miR-29a upregulation on ovarian dysfunction." (PMID 35845134, 2022).
retinoblastoma (1 paper, 2005). A malignant tumor that originates in the nuclear layer of the retina. "It has previously been established that HBP1 is a target of the retinoblastoma pathways and that HBP1 negatively regulates Wnt/β-catenin, thus inhibiting proliferation and suggesting that HBP1 may have a tumour suppressor function." (PMID 16001974, 2005).
steatosis (1 paper, 2018). Increased lipid within the cytoplasm of cells. "Recently, miR-21 has been proposed to play a role in steatosis progression towards HCC by inhibiting HMG-Box Transcription Factor 1 (HBP1)." (PMID 30544653, 2018).
testicular teratoma (1 paper, 2017). "We observed one instance of testicular teratoma in a chimeric male founder, but this phenomenon did not affect any of the Hbp1+/- males in the established colony (0/53 males)." (PMID 28107452, 2017).
tongue squamous cell carcinoma (1 paper, 2017). A squamous cell carcinoma that arises from the tongue. "Reduced expression of both FOXO1 and HBP1 was also found in two tongue squamous cell carcinoma datasets in the Oncomine database." (PMID 28099936, 2017).
triple-negative breast carcinoma (1 paper, 2025). An invasive breast carcinoma which is negative for expression of estrogen receptor (ER), progesterone receptor (PR), and human epidermal growth factor receptor 2 (HER2). "MiR-3662 has also been implicated in triple-negative breast cancer, by targeting HBP1, a tumor suppressor that inhibits the Wnt/β-catenin signaling pathway." (PMID 40862714, 2025).
tumor (42 papers, 2005 to 2025). "HBP1-deficient mice had more liver tumor tissue blocks, and the tumor tissue volume was larger compared with wild-type mice." (PMID 33794968, 2021). "Hbp1 was proposed to function as a tumor suppressor and has been implicated in regulating cell cycle exit." (PMID 29911972, 2018). "Of note, the expression of previously well-established in vitro targets of miR-21 having tumor-suppressive activity, i.e., Ppara, Pdcd4, Timp3, Spry2, Pten, and Hbp1, was unchanged with miR-21 deficiency in vivo in mice again highlighting a cell/organ context-dependent action of miR-21." (PMID 34638467, 2021). "By suppressing HBP1, miR-3662 activates Wnt/β-catenin signaling, promoting tumor progression and metastasis." (PMID 40862714, 2025). "HBP1 was previously identified as a transcription factor and a tumor suppressor that inhibits the proliferation of cancer cells." (PMID 38924383, 2024). "In this study, we found that transcription factor HBP1 has a novel function of reducing the antioxidant capacity of tumor cells." (PMID 37406020, 2023). "In the present study, we demonstrate that HBP1 can be methylated by PRMT1 at R378, which alleviates HBP1-mediated repression of tumor metastasis and growth through regulation of GSN expression." (PMID 35941115, 2022). "Taken together, these results suggest that methylation of HBP1 can promote glycolysis by accelerate rearrangement of the cytoskeleton, thereby provide more energy for growth and metastasis of tumor cells." (PMID 35941115, 2022). "This investigation elucidates the mechanism of how methylated HBP1 facilitates actin cytoskeleton remodeling, thus attenuates its tumor-suppressive function and promotes tumor progression." (PMID 35941115, 2022). "PRMT1-mediated methylation of HBP1 alleviates the repressive effects of HBP1 on tumor metastasis and growth." (PMID 35941115, 2022). "With this diverse set of HBP1 interactions and targets in cells, it will be of great importance to examine the role of HBP1 methylation in tumor initiation and progression." (PMID 35941115, 2022). "The overexpression of HBP1 arrests cell cycle and inhibits tumorigenesis, which implies that HBP1 functions as a tumor suppressor." (PMID 36326689, 2022). "Subsequently, we utilized PRMT1 mutant G98R, which has lost its enzymatic activity, to test its role in HBP1 methylation and tumor cell metastasis and growth." (PMID 35941115, 2022). "Overall, our results suggest that HBP1 methylation alleviates its suppression of tumor cell metastasis and growth." (PMID 35941115, 2022). "Collectively, our data suggest that PRMT1-mediated HBP1 methylation facilitates PRMT1-induced metastasis in tumor cells." (PMID 35941115, 2022). "R378A expression resulted in a noticeably stronger suppression of tumor growth compared with wild-type HBP1 or empty vector in the xenograft models." (PMID 35941115, 2022). "Methylation of HBP1 promotes actin cytoskeleton remodeling, glycolysis and tumor progression by downregulating GSN (a vital actin-binding protein) levels." (PMID 35941115, 2022). "The investigation in tumour cells indicated that HBP1 efficiently regulates Wnt signalling pathway to inhibit cell proliferation through the suppression of TCF‐β‐catenin complex." (PMID 33769664, 2021). "The expression level of HBP1 decreased with the increase of tumor TNM stage, and the survival rate after surgery also decreased." (PMID 33794968, 2021). "In previous studies, HBP1 was described as a tumor suppressor that is activated by p38-MAPK and Pim-1, leading to premature cell decay and apoptosis." (PMID 33794968, 2021). "The HMG‐box transcription factor HBP1 is identified as a tumour suppressor that negatively regulates the cell cycle." (PMID 33769664, 2021). "HBP1 is a ubiquitous transcription factor, and plays significant roles in senescence, apoptosis, differentiation termination, and tumor suppression in various cell types." (PMID 33407952, 2021).
tumor (continued). "It is firstly reported that HBP1 knockdown inhibited the proliferation and metastasis of NPC, which indicates that HBP1 functions as a non-tumor suppressor gene in NPC." (PMID 29367693, 2018). "HMG-box transcription factor 1 (HBP1) has been reported to be a tumor suppressor in diverse malignant carcinomas." (PMID 29367693, 2018). "When the mice were sacrificed, the tumor was removed and measured; the tumor in HBP1 shRNA group was significantly bigger than Con shRNA group." (PMID 26942107, 2016). "The results uncovered roles for several tumor suppressors, including HBP1, in the augmentation of mitochondrial function." (PMID 27206316, 2016). "Lastly, a composite module (score: 47.63) for up-regulated DEGs in non-tumor transgenic lung was computed and consisted of Myc, Hbp1 and Hif1." (PMID 26427040, 2015). "The immunohistochemistry data indicated that 30.5% (25/82) of tumours from NSCLC patients showed absence or low expression of HBP1 protein." (PMID 24895061, 2014). "Here, we demonstrate that HBP1 acts as a tumour suppressor and serves as a prognostic biomarker in NSCLC clinical and cell models." (PMID 24895061, 2014). "Methylation-specific PCR assay showed that 53.7% (44/82) of tumours exhibited promoter hypermethylation of HBP1 gene." (PMID 24895061, 2014). "HBP1 has the properties of a tumor suppressor; this tumor suppressor activity is likely due to the ability of HBP1 to transcriptionally repress cell cycle regulators and the pro-inflammatory macrophage migration inhibitory factor." (PMID 23613959, 2013). "Notably, Blv-miR-B4-3p, which shares a seed sequence with the host miRNA miR-29a, is known for downregulating the tumor suppressor genes HMG-box transcription factor 1 (HBP1) and peroxidasin homologs (PXDN) in B-cell tumors." (PMID 38254466, 2024). "Blv-miR-B4-3p shares seed sequence similarities with the host miRNA miR-29a, which is known to downregulate the expression of two tumor suppressor genes, the genes coding for the HMG-box transcription factor 1 (HBP1) and for the peroxidasin homolog (PXDN), in B-cell tumors." (PMID 37268923, 2023). "Our results suggest that HBP1 methylation may accelerate rearrangement of the cytoskeleton by promoting filament formation, and ultimately support the growth and metastasis of tumor cells." (PMID 35941115, 2022). "To investigate the mechanism controlling how HBP1 methylation regulates tumor cell metastasis and growth, we performed RNA sequencing (RNA-seq) analysis in HeLa cells expressing wild-type HBP1 or R378A, then clustered the same or similar gene expression patterns with hierarchical cluster analysis." (PMID 35941115, 2022). "Hence, our results suggest that methylation of HBP1 can promote actin cytoskeleton remodeling, thus inducing growth and metastasis of tumor cells by downregulating GSN expression." (PMID 35941115, 2022). "Thus, we conclude that pharmacological or enzymatic inhibition of HBP1 methylation can suppress tumor cell metastasis and growth." (PMID 35941115, 2022). "Our experiments revealed that two PRMT1-specific inhibitors (AMI-1 and MS023) could decrease HBP1 methylation and increase HBP1 protein levels, thereby enhancing HBP1-mediated suppression of tumor growth and metastasis." (PMID 35941115, 2022). "Because PRMT1-mediated HBP1 methylation can promote metastasis and growth of tumor cells, we next asked if pharmacological inhibition of HBP1 methylation could suppress tumor cell metastasis and growth." (PMID 35941115, 2022). "As a tumor suppressor, HBP1 expression levels are often low in various cancers." (PMID 35941115, 2022). "So we ask question whether methylated HBP1-mediated actin cytoskeletal remodeling promotes glycolysis in tumor cells?" (PMID 35941115, 2022).
tumor (continued). "HBP1 plays a role in the regulation of the cell cycle and is a tumor suppressor." (PMID 34777463, 2021). "Even through the relationship between HBP1 and Wnt had been studied in other tissue, especially tumor tissues, its role in islet cells were largely unknown to us." (PMID 31969494, 2020). "Given that HBP1 is a tumor suppressor, MDM2 might affect tumorigenesis and response to oncogenic growth factor signaling by downregulation of HBP1." (PMID 30816344, 2019). "HBP1 was originally identified as a tumor inhibitor and a p38 MAPK-inducible protein." (PMID 30816344, 2019). "This is the first report to show that HBP1 may have a novel tumor-promoting role in NPC development and invasion." (PMID 29367693, 2018). "IHC staining indicated that HBP1 expressed lower levels in the tumor tissues from the miR-29c agomir-injected mice and higher HBP1 expression levels than in the NC agomir group; additionally, the cells of cellular proliferative nuclear antigen Ki67-stained were decreased." (PMID 29367693, 2018). "FOXO1 and HBP1 may exert their tumor suppression function through the induction of growth arrest and apoptosis." (PMID 28099936, 2017). "Together, these findings suggest a role of HBP1 in tumor suppression." (PMID 28099936, 2017). "Similarly, tumor suppressor HMGbox transcription factor 1 (HBP1) whose expression is halved in sheep tumor cells is unaffected in bovine B-lymphocytes expressing the BLV miRNAs." (PMID 27123579, 2016). "Furthermore, the expression of HBP1 in tumor was detected via western blot; we found that HBP1 expression was greatly decreased in HBP1 shRNA group." (PMID 26942107, 2016). "The multiple mechanisms are involved in HBP1-mediated senescence induction and tumor inhibition." (PMID 27129219, 2016). "Among the nude mice stably transfected with Con shRNA cells and HBP1 shRNA cells, the knockdown of endogenous HBP1 could effectively promote the tumor size compared with the Con shRNA cells." (PMID 26942107, 2016). "By regulating the transcription of various genes, HBP1 has been found to participate in multiple cell progressions, including cell cycle inhibition, terminal differentiation, senescence induction, and tumor suppression, in a variety of tissues and cell types (19, –, 21)." (PMID 27129219, 2016). "Thus, both functions of HBP1 were synergistic and required for enacting senescence and tumor inhibition." (PMID 27129219, 2016). "It was shown earlier that Hbp1 functions as a tumor suppressor by inhibiting oncogenic Wnt-β-catenin signaling while oncogenic c-Myc activity is inhibited by its interaction with the tumor suppressor protein Hbp1." (PMID 26427040, 2015). "HBP1 may function as a tumour suppressor by inhibiting the Wnt/β-catenin signalling to block the oncogenic phenotype." (PMID 24895061, 2014). "Thus, we hypothesized that PRMT1-mediated HBP1 methylation may participate in PRMT1-induced metastasis in tumor cells." (PMID 35941115, 2022). "Furthermore, miR-29c inhibited NPC tumor growth while HBP1 expedited tumorigenesis in vivo." (PMID 29367693, 2018). "It has been reported that HBP1 could be a target gene of miR-19a and miR-17–5p in tumor cells." (PMID 28935967, 2017). "To examine whether HBP1 is altered and associated with the clinical characteristics of the NSCLC patients, we first examined the protein expression level of HBP1 and β-catenin in 82 tumours from NSCLC patient by immunohistochemical analysis." (PMID 24895061, 2014). "For example, HBP1 is a transcription factor of the HMG box family and functions as a tumor suppressor, which showed lower expression in several tumor types relative to matched normal tissues (Bollaert, De Rocca Serra & Demoulin, 2019)." (PMID 35178306, 2022). "The transcription factor HBP1 belongs to the sequence-specific high mobility group (HMG) family and functions as a tumor suppressor." (PMID 33794968, 2021).